TPTE2P1 (TPTE2 pseudogene 1)
Gene: Transcribed unprocessed pseudogene on chromosome 13 (24,951,388 to 24,967,454, reverse strand). Ensembl gene ENSG00000253771.
Diseases named in the same sentence as TPTE2P1 in open-access papers:
TPTE2P1 is named in the same sentence as 2 diseases in open-access papers, as found by Europe PMC text mining. Sharing a sentence is not in itself a finding about the gene and the disease. The quoted sentences say what the papers report.
colorectal cancer (1 paper, 2020). A primary or metastatic malignant neoplasm that affects the colon or rectum. "The authors also indicated that silencing expression of TPTE2P1 resulted in cell cycle arrest at S phase and caused cell apoptosis in colorectal cancer." (PMID 32185172, 2020). "TPTE2P1 levels in colorectal cancer tissues were higher than that in adjacent normal tissues, and its upregulation was markedly associated with poor patients’ survival." (PMID 32185172, 2020).
gallbladder cancer (1 paper, 2020). "Two pseudogene-derived lncRNAs, TPTE2P1 and Loc344887, have been documented to play oncogenic roles in development of gallbladder cancer." (PMID 32185172, 2020). "Depletion of TPTE2P1 significantly blocked epithelial-mesenchymal transition, migration and invasion of gallbladder cancer." (PMID 32185172, 2020).